DPP4 (dipeptidyl peptidase 4)
Description:
Cell surface glycoprotein receptor involved in the costimulatory signal essential for T-cell receptor (TCR)-mediated T-cell activation. Acts as a positive regulator of T-cell coactivation, by binding at least ADA, CAV1, IGF2R, and PTPRC. Its binding to CAV1 and CARD11 induces T-cell proliferation and NF-kappa-B activation in a T-cell receptor/CD3-dependent manner. Its interaction with ADA also regulates lymphocyte-epithelial cell adhesion. In association with FAP is involved in the pericellular proteolysis of the extracellular matrix (ECM), the migration and invasion of endothelial cells into the ECM. May be involved in the promotion of lymphatic endothelial cells adhesion, migration and tube formation. When overexpressed, enhanced cell proliferation, a process inhibited by GPC3. Also acts as a serine exopeptidase with a dipeptidyl peptidase activity that regulates various physiological processes by cleaving peptides in the circulation, including many chemokines, mitogenic growth factors, neuropeptides and peptide hormones such as brain natriuretic peptide 32. Removes N-terminal dipeptides sequentially from polypeptides having unsubstituted N-termini provided that the penultimate residue is proline. (Microbial infection) Acts as a receptor for human coronavirus MERS-CoV-2.
Synonyms: CD26; ADCP2; DPPIV; ADABP; TP103
Tractability: Small molecule: an approved drug acts on it; a structure with a bound ligand is known; a high-quality ligand is known; it has a high-quality binding pocket; it belongs to a druggable protein family. Antibody: a drug acting on it is in phase 2 or 3 trials; UniProt places it where antibodies can reach, with high confidence; its Gene Ontology location is reachable by antibodies, with high confidence; UniProt predicts a signal peptide or a membrane-spanning region. PROTAC: its protein half-life has been measured; a small molecule that binds it is known.
Target class: Enzyme; Serine protease SC clan; Protease; Serine protease S9B subfamily; Serine protease
Chemical probes: ALOGLIPTIN (high quality), RESVERATROL, SITAGLIPTIN (high quality)
Gene: Protein-coding gene on chromosome 2 (161,992,244 to 162,074,394, reverse strand). Ensembl gene ENSG00000197635.
Subcellular location: Secreted (Dipeptidyl peptidase 4 soluble form); Cell membrane; Apical cell membrane; Cell projection, invadopodium membrane; Cell projection, lamellipodium membrane; Cell junction; Membrane raft
Pathways (Reactome):
Metabolism of proteins: Synthesis, secretion, and inactivation of Glucagon-like Peptide-1 (GLP-1); Synthesis, secretion, and inactivation of Glucose-dependent Insulinotropic Polypeptide (GIP)
Gene Ontology:
Molecular function: chemorepellent activity; dipeptidyl-peptidase activity; identical protein binding; protease binding; protein binding; protein homodimerization activity; serine-type endopeptidase activity; serine-type peptidase activity; signaling receptor binding; tripeptidyl-peptidase activity; virus receptor activity
Biological process: endothelial cell migration; negative regulation of extracellular matrix disassembly; negative regulation of neutrophil chemotaxis; positive regulation of cell population proliferation; proteolysis; regulation of cell-cell adhesion mediated by integrin; response to hypoxia; T cell activation; T cell costimulation; glucagon processing; membrane fusion; peptide hormone processing; receptor-mediated endocytosis of virus by host cell; receptor-mediated virion attachment to host cell; symbiont entry into host cell; negative chemotaxis
Cellular component: anchoring junction; apical plasma membrane; cell surface; endocytic vesicle; extracellular exosome; extracellular region; focal adhesion; lamellipodium; lysosomal membrane; membrane; membrane raft; plasma membrane; intercellular canaliculus; lamellipodium membrane
Genetic constraint (gnomAD): Loss-of-function variants: 69 observed, 93.6 expected, observed/expected ratio (o/e) 0.74, 90% interval 0.61 to 0.9. The upper end of that interval is the gene's LOEUF score, 0.9, which puts it in group 3 of 6, group 1 being the genes least tolerant of losing a copy. Missense variants: 723 observed, 772.07 expected, observed/expected ratio (o/e) 0.94, 90% interval 0.88 to 1. Synonymous variants: 263 observed, 262.47 expected, observed/expected ratio (o/e) 1, 90% interval 0.9 to 1.11.
Homologues: Orthologues: chimpanzee DPP4 (99% identical), macaque DPP4 (98% identical), pig DPP4 (88% identical), dog DPP4 (88% identical), guinea pig DPP4 (88% identical), rat Dpp4 (85% identical), mouse Dpp4 (84% identical), tropical clawed frog fap (58% identical), zebrafish dpp4 (55% identical), Drosophila melanogaster ome (32% identical), Caenorhabditis elegans dpf-1 (25% identical), zebrafish zgc:136971 (14% identical). Paralogues in human: FAP (51% identical), DPP10 (34% identical), DPP6 (31% identical), DPP8 (24% identical), DPP9 (23% identical), APEH (14% identical).
Diseases named in the same sentence as DPP4 in open-access papers:
DPP4 is named in the same sentence as 595 diseases in open-access papers, as found by Europe PMC text mining. Sharing a sentence is not in itself a finding about the gene and the disease. The quoted sentences say what the papers report.
diabetes (1,266 papers, 2009 to 2026). "We report a case of DPP-4 inhibitor-associated BP presenting primarily with gingival lesions in a 76-year-old woman with type 2 diabetes mellitus treated with teneligliptin." (PMID 41988607, 2026). "Identifying a highly specific autoantibody response targeting the NC7-Col4 region in DPP4i-BP suggests the potential use of this epitope as a biomarker for early detection or risk stratification in patients with diabetes treated with DPP4 inhibitors." (PMID 40749047, 2025). "Of note, our subgroup analysis of patients using insulin, who typically have more advanced diabetes and higher mortality risk, showed a significant survival benefit in those also taking DPP-4 inhibitors." (PMID 40869643, 2025). "Metformin and DPP-4 inhibitors ranked second and third, with most associations linked to increased response to them in people with diabetes mellitus." (PMID 41149843, 2025). "Both bedtime NPH insulin and incretin-based therapy with dipeptidyl peptidase 4 (DPP4) inhibitors are recommended by the American Diabetes Association for use in selected populations, particularly in older adults and individuals in low-resource settings." (PMID 41282288, 2025). "Pre-existing conditions: Some drugs (e.g., GLP-1 analogs, DPP-4 inhibitors) are mainly used by diabetic patients, and diabetes is an independent risk factor for pancreatitis." (PMID 40308779, 2025). "Recent studies emphasize the neuroprotective potential of dipeptidyl peptidase 4 (DPP4i) inhibitors, pointing toward a promising avenue for intervention in addressing cognitive challenges associated with diabetes." (PMID 38860903, 2025). "Elevated DPP4 activity and concentration have been implicated in several metabolic disorders, including obesity, FL, type 2 diabetes mellitus (T2DM), and coronary artery disease (CAD)." (PMID 40249657, 2025). "Epidemiological studies report an elevated risk of Parkinson's disease (PD) in patients with type 2 diabetes mellitus (T2DM) that is mitigated in those prescribed dipeptidyl peptidase 4 (DPP-4) inhibitors." (PMID 38563864, 2024). "In literature, DPP-4 inhibitors show mixed results regarding the association with COVID-19 death and hospitalization in diabetes mellitus patients." (PMID 38538694, 2024). "In a systematic review of drug-associated BP, the strongest evidence was observed with DPP4 inhibitors, an oral hypoglycemic agent used to treat type 2 diabetes mellitus." (PMID 39712738, 2024). "Linagliptin is commonly used clinically in the treatment of type 2 diabetes mellitus in an oral form, and it has been shown that the risk of hypoglycemia caused by the DPP4 inhibitor is very low." (PMID 38762508, 2024). "CD26/DPP4 inhibitors have been used clinically as therapeutic agents against diabetes, which can be associated with pulmonary hypertension." (PMID 39684311, 2024). "Active TGFβ signaling and elevated dipeptidyl peptidase-4 (DPP-4) levels are causative pathways that accelerate renal fibrosis in diabetes." (PMID 39630889, 2024). "Association Between Dipeptidyl Peptidase-4 Inhibitors and Diabetic Retinopathy in Korean Patients With Type 2 Diabetes Mellitus: Nationwide Population-Based Cohort Study, 17 August, 2021) this was taken into consideration." (PMID 39295783, 2024). "Current interest in the effects of incretin-based therapy, including GLP-1 receptor agonists and dipeptidyl peptidase-4 inhibitors, is intense due to effects on weight loss, as well as diabetes treatment." (PMID 38755184, 2024). "This manuscript provides a comprehensive review of the dermatological side effects associated with DPP-4 inhibitors; a class of medications used in diabetes management." (PMID 38523307, 2024). "miR-29 family members have emerged as key players that are associated with targeting DPP-4 mRNA in endothelial cells in diabetes." (PMID 39630889, 2024).
diabetes (continued). "Bone marrow adipocyte lineage cells are capable of expressing dipeptidyl peptidase 4 (DPP4), a protease associated with diabetes treatment, which is negatively correlated with bone mass, but no clear mechanism has been proposed." (PMID 39006365, 2024). "During the family screening, the mutation was found in her father who developed diabetes at the age of 36 and was also being treated with oral therapy for diabetes (metformin and dipeptidyl peptidase 4 inhibitor)." (PMID 37511676, 2023). "The results of the crosstabulation analysis suggest that CKD, metformin, and DPP4 inhibitor treatment are significantly associated with acute kidney injury in COVID-19 patients with diabetes." (PMID 37374918, 2023). "CTRB1, which encodes chymotrypsinogen via incretin pathway, has been shown to be associated with the development of diabetes and response to DPP-4 inhibitor treatment." (PMID 38027148, 2023). "This cohort study of 104 462 patients with diabetes in Taiwan found that SGLT2i use vs dipeptidyl peptidase 4 inhibitor (DPP4i) use was associated with reductions of 34% and 44% in the risk of AKI and AKI requiring dialysis." (PMID 36811856, 2023). "A meta-analysis of four retrospective cohorts of patients with type 2 diabetes mellitus (T2DM) found that DPP4 inhibitor users had a 28% lower risk of incident RA compared with those who did not receive DPP4 inhibitors." (PMID 37052755, 2023). "Authors have concluded that the excitement surrounding DPP-4 inhibitors is justified because in addition to controlling blood glucose level, they are good at managing risk factors associated with diabetes." (PMID 37287751, 2023). "DPP4 inhibitors, which are oral antidiabetic agents for treating type 2 diabetes mellitus, were suggested to increase the risk of BP." (PMID 36685490, 2022). "With aging, diabetes, obesity, and menopause status were risk factors for osteoporotic and bone fractures, thus it is hard to conclude the association between DPP4 inhibitors and bone metabolism from the current clinical evidence." (PMID 35586625, 2022). "It has been believed that elevated DPP-4 expression in type 2 diabetes mellitus is the cause of high disease morbidity and mortality in Covid-19." (PMID 36199855, 2022). "Undoubtedly, part of the association between sDPP4 and T2DM is mediated by higher sDPP4 levels in the presence of obesity, which represents a common determinant of elevated DPP4 release and increased risk of insulin resistance and diabetes onset." (PMID 36140405, 2022). "Since the approval of DPP4 inhibitors for treatment of T2DM, the interest on alternate physiological effects of the enzyme and on context-sensitive association of DPP4 features with diabetes and other conditions has increased." (PMID 36197412, 2022). "This work represents the first study demonstrating the alleviation effect of DPP-4 inhibitor on cognitive dysfunction caused by diabetes." (PMID 39280108, 2022). "We included only studies with a comparator diabetes drug with low risk of hypoglycaemia (metformin, DPP-4 inhibitors, SGLT-2 inhibitors and GLP-1 receptor agonists)." (PMID 36261824, 2022). "The cohort study, involving 340 participants and lasting five years, reported that using a DPP-4 inhibitor was linked with a decreased risk of fractures due to any cause and fracture of the upper limbs in patients suffering from type 2 diabetes mellitus." (PMID 36140292, 2022). "Is use of glucagon-like peptide-1 (GLP-1) receptor agonists among patients with diabetes and advanced-stage chronic kidney disease or end-stage kidney disease associated with better outcomes than use of dipeptidyl peptidase-4 (DPP-4) inhibitors?" (PMID 35254430, 2022). "Recent literature survey revealed that various classes of drugs like sulfonylureas, biguanides, thiazolidinediones, and dipeptidyl peptidase-4 (dpp-4) inhibitors are used for the management of diabetes but most of these are associated with obnoxious effects." (PMID 35388310, 2022).
diabetes (continued). "We investigated the association between all types of diabetes medications (focused on DPP-4 inhibitors) and BP using the data from FAERS based on DMAs in this study." (PMID 33850463, 2021). "Some studies suggested the association of diabetes medications with Bullous Pemphigoid (BP), especially the Dipeptidyl Peptidase 4 (DPP-4) inhibitors." (PMID 33850463, 2021). "The study aims to detect an association between diabetes medications (focusing on DPP-4 inhibitors) and bullous pemphigoid based on FDA Adverse Event Reporting System (FAERS)." (PMID 33850463, 2021). "According to an observational study conducted in Taiwan, the risk factors of bullous pemphigoid in patients with type 2 diabetes mellitus seemed to be associated with using DPP4 inhibitors, having dementia and taking spironolactone." (PMID 33995274, 2021). "DPP4 (CD26) is a membrane-anchored protease linked to diabetes and implicated as a cofactor in SARS-CoV-2 uptake." (PMID 33919584, 2021). "In our previous report, we had demonstrated DPP-4 mediates the insulin resistance signals, leading to the pathological phenomenons associated with diabetes and its complications." (PMID 33267804, 2020). "In susceptibility toward diabetes, dipeptidyl peptidase-4 (DPP-4) degrades the incretin and involve in insulin resistance." (PMID 32815547, 2020). "Type 2 diabetes mellitus is a well-known risk factor for cognitive impairment, and the neuroprotective effects of DPP-4 inhibitors have been proved." (PMID 32368255, 2020). "Polymorphisms in the DPP4 gene were implicated in several diseases and conditions, including diabetes and myocardial infarction but their potential impact on MERS-CoV infection has not been analyzed." (PMID 31964246, 2020). "A link between obesity or underlying diseases like diabetes mellitus, which both can affect DPP4 expression levels, and the risk of fatal outcome of MERS-CoV infection has been made." (PMID 31964246, 2020). "In multivariable regression analyses, age, diabetes duration, BMI, HbA1c, the use of metformin, sulfonylurea derivatives and DPP4 inhibitors were negatively associated with serum magnesium concentrations." (PMID 31650393, 2020). "Use of DPP-4 inhibitors has been associated with an increased risk of inflammatory bowel disease compared with other diabetes drugs (53.4 vs. 34.5 per 100,000 person-years, HR 1.75, 95% CI 1.22–2.49) in a population-based study." (PMID 31366085, 2019). "We have shown that both metformin and dipeptidyl peptidase 4 inhibitor decrease the risk of AF in patients with diabetes in a nationwide cohort study." (PMID 31558158, 2019). "Some studies indicate possible beneficial effects of DPP-4 inhibitors on renal complications caused by diabetes." (PMID 30333575, 2018). "It has also been shown to inhibit dipeptidyl peptidase-4 (DPP-4), which is a membrane glycoprotein and serine exopeptidase that is implicated in type 2 diabetes mellitus through its activity inhibiting incretin release, including GLP-1." (PMID 29023392, 2017). "Background and Objectives: Limited research focuses on the risk of ischemic cerebrovascular disease associated with use of dipeptidyl peptidase-4 inhibitors (DPP-4 inhibitors) in patients with type 2 diabetes mellitus in Taiwan." (PMID 29213240, 2017). "In this study, the risk of hospitalization due to CVD for DPP-4 inhibitors was evaluated with diabetes durations of <1 year, 1 to 2.5 years, and >2.5 years." (PMID 28640111, 2017). "The result showed that DPP-4 inhibitors showed decreased cardiovascular risk with a long diabetes duration (>2.5 years), compared with glimepiride." (PMID 28640111, 2017). "We also found several noteworthy results about an association between diabetes duration and DPP-4 inhibitors." (PMID 28640111, 2017). "Plasma dipeptidyl-peptidase-4 activity (DPP4a) is inversely associated with left ventricular function in patients with heart failure (HF) or diabetes." (PMID 28733630, 2017).